CRP (C-reactive protein)
Diseases named in the same sentence as CRP in open-access papers (continued):
Sharing a sentence is not in itself a finding about the gene and the disease.
Obesity (continued). "Recent studies demonstrated that elevated serum CRP levels were associated with obesity and insulin resistance." (PMID 21076541, 2010). "We believe that it is not easy to determine the effect of polymorphism on serum levels of CRP, because serum CRP levels are associated with a number of factors, such as age, smoking habits, alcohol consumption, stress, blood pressure, and obesity." (PMID 19398847, 2009). "First, individuals with obesity are at increased risk for various chronic diseases, several are also characterized by elevated CRP." (PMID 22505974, 2009). "In all examined cohorts higher concentration of CRP was associated with increased prevalence of obesity and smoking, as well as lower prevalence of physical activity." (PMID 18714384, 2008). "CRP is strongly associated with obesity, and weight loss has been shown to decrease CRP in nine of ten studies in which it has been evaluated." (PMID 19690638, 2007). "Additionally, TBARS, IL-8, IL-10, and CRP were identified as independent risk factors for obesity, where vitamin D was identified as an independent protective factor." (PMID 42213218, 2026). "Furthermore, it is known that insulin resistance and CRP are associated with excess body fat, and overweight and obesity are causes of low relative HGS." (PMID 41522289, 2026). "Regarding the effect of inflammation on telomere length values in obesity, the increase in BMI seems to trigger the increased secretion of inflammatory mediators, including fibrinogen, C-reactive protein (CRP), IL-6, and TNF-α, which in turn cause accelerated telomere shortening." (PMID 40566527, 2025). "Some researchers have suggested that obesity may be associated with chronic low-grade inflammation, with ultrasensitive C-reactive protein having been shown to correlate with BMI." (PMID 40077689, 2025). "The CRP levels can also be considered a risk factor for obesity." (PMID 40722558, 2025). "The association between increased IL-6 and Hs-CRP levels and obesity in this study supports the hypothesis that inflammation plays a significant role in obesity-related metabolic dysfunctions." (PMID 40641901, 2025). "CONCLUSION: ADA-A were uncommon, and their presence may be associated with obesity, increased C-reactive protein, and poorer patient-reported health." (PMID 41447414, 2025). "Additionally, inflammatory markers like C-reactive protein (CRP) are commonly elevated in individuals with obesity and are associated with an increased risk of cardiovascular disease." (PMID 40632711, 2025). "CRP, a well-known acute-phase protein, is elevated duringinflammatory responses and has been directly associated with the pro-inflammatorystate observed in both obesity and depression." (PMID 40926826, 2025). "One report suggested that CRP levels are more closely associated with hepatic fat content than with obesity itself, implying that NAFLD may contribute to increased CRP levels." (PMID 41150798, 2025). "Our findings also elucidated that the loneliness–NAFLD and social isolation–NAFLD associations were partially mediated through obesity, current smoking, irregular physical activity, suboptimal sleep duration, and depression, as well as inflammatory biomarkers like CRP and immune cell counts." (PMID 39780850, 2025). "IR itself is associated with obesity, dyslipidemia, hypertension, and increased cardiovascular risk, while elevated inflammatory markers such as CRP and IL-6 reflect a chronic low-grade inflammatory state that may further amplify multiorgan involvement." (PMID 41302170, 2025). "Adherence to vegetarian and vegan dietary patterns has been linked to reductions in BMI, TC, LDL cholesterol, glucose levels, and serum C-reactive protein (CRP), along with a reduced risk of cardiovascular diseases, obesity, type 2 diabetes, and certain cancers." (PMID 40422620, 2025).
Obesity (continued). "Furthermore, obesity is linked to elevated levels of inflammatory mediators, including C-reactive protein (CRP), tumor necrosis factor-α (TNF-α), and interleukin-6 (IL-6)." (PMID 41163684, 2025). "Moreover, insecure and disorganized attachment in early infancy has been associated with higher CRP levels in early childhood and predicted later obesity compared to children with secure attachment." (PMID 40724779, 2025). "Moreover, a recent study has documented elevated CCL19 levels in correlation with CRP among individuals with obesity, indicating a potential association with systemic inflammation." (PMID 40076884, 2025). "It is possible that these effects may also be due to MPO, CRP, or other inflammatory or oxidative mediators associated with obesity." (PMID 40900465, 2025). "In fact, a rise in circulating ANGPTL2 levels bears a close association with C-reactive protein expression in obesity and an increase in expression of pro-inflammatory TNF-α and its receptor TNFR1 in the onset and progression of T2D, obesity, and heart failure." (PMID 40427505, 2025). "However, higher CRP is strongly associated with obesity, highlighting the relevance of alterations in body composition." (PMID 41036582, 2025). "Besides, smoking, aging, hypercholesterolemia, hypertension, hyperglycemia and family history of early atherosclerotic disease, obesity, high CRP, and chronic systemic infection are also associated with arterial stiffness." (PMID 40080791, 2025). "However, it is well established that obesity is associated with an elevated CRP; for example, in a large cohort of smokers, the influence of obesity over CRP predominated." (PMID 40842041, 2025). "However, the clinical value of CRP is questionable, as it is susceptible to confounding by obesity and metabolic syndrome, which are also highly prevalent comorbidities found in HS patients." (PMID 41458786, 2025). "Similarly, the positive relationship between BMI and CRP/Alb underscores systemic inflammation and metabolic risk in individuals with obesity." (PMID 41302334, 2025). "Inflammation reflected by pain and CRP may be a key mechanism affecting insulin resistance and frailty risk or reversion in China, although metabolic diseases represented by obesity may become a priority in the United States." (PMID 40245241, 2025). "Obesity (β = 0.39, p < 0.001) at baseline was significantly associated with higher LV mass index at follow-up in multivariable analyses, after adjustment for age, sex, CRP and b/tsDMARD therapy at follow-up." (PMID 41141372, 2025). "Since obesity is a systemic low-grade inflammation associated with increased plasma levels of inflammatory markers including C-reactive Protein (CRP) and IL-6, the potential role of DHA as an anti-inflammatory agent has to be investigated in children with obesity." (PMID 39186221, 2025). "Further research focusing on the roles of LDL, OXLDL, MPO, and CRP may provide deeper insights into the mechanisms underlying microvascular dysfunction in obesity." (PMID 40900465, 2025). "In conclusion, age (> 40 years), sex, race, cigarette smoking, obesity, elevated CRP and LDL-cholesterol levels, and 25(OH)D deficiency are some of the risk factors associated with the pathogenesis of PsA within the context of a South African population consisting of Caucasians and Indians." (PMID 39792433, 2025). "Similarly, cohort data indicate that severe OSA independently increases the likelihood of CRP > 3 mg/L, with this association being further amplified by coexisting obesity." (PMID 41517522, 2025). "Moreover, other studies emphasised that elevated CRP and IL-6 levels are associated with an increased risk of HF in individuals with obesity and metabolic syndrome." (PMID 40814000, 2025). "POD3 CRP < 150 mg/l was also associated with obesity (p < 0.01)." (PMID 40042780, 2025).
Obesity (continued). "Men with risk factors (obesity, sedentary life, smoking) often show higher IL-6/CRP levels than comparably affected women, while higher CRP concentrations in premenopausal women appear to result from their greater accumulation of subcutaneous fat compared to men." (PMID 41425557, 2025). "The association between CRP and childhood obesity/overweight could be supported because obesity is characterized by chronic inflammation at a low-grade level, and CRP is an acute-phase inflammatory compound." (PMID 40565251, 2025). "Furthermore, the DASH diet has been shown to effectively decrease inflammation markers linked to obesity, such as hs-CRP levels, when compared to unhealthy or customary diet." (PMID 38476230, 2024). "Furthermore, obesity is associated with increased levels of circulating acute-phase reactants, such as C-reactive protein (CRP), which further supports the presence of systemic inflammation." (PMID 38790590, 2024). "Obesity and obesity-associated diseases are linked with elevated CRP levels." (PMID 38573884, 2024). "Other proposed mechanisms for the association between obesity and lung function impairmentinclude systemic inflammation, where levels of pro-inflammatory markers such asinterleukin-6, C-reactive protein, fibronectin and other cytokines are increased in peoplewith airway obstruction." (PMID 38097206, 2024). "Previously, we and others reported that the increased adipose expression of CXCL10 in individuals with obesity was associated with inflammatory (IL-1β expression, C-reactive protein levels) and other factors (BMI, CXCR3, and reduced neovascularization causing adipose tissue hypoxia)." (PMID 39065674, 2024). "CRP level was positively correlated with an increased risk of both types of obesity." (PMID 39599620, 2024). "On the other hand, obesity in COPD patients has been associated with increased C-reactive protein." (PMID 38651412, 2024). "Diacylglycerols are associated with a reduction in obesity and adverse cardiovascular events since they decrease the levels of C-reactive protein (CRP), tumor necrosis factor-alpha (TNF-α), fat accumulation, and platelet aggregation, which are considered CVD risk factors." (PMID 39408727, 2024). "Another possibility is that other inflammatory markers or signaling pathways may promote the observed association between obesity and hs-CRP levels, independently of TNF-α." (PMID 38550672, 2024). "Some of the highly synthesized IgG autoAbs that were depleted in the BAFF-neutralized mice target C-reactive protein, tissue transglutaminase, aquaporin 4, and complement C1q, and these proteins are associated with obesity-induced WAT inflammation and increase in IR." (PMID 39185417, 2024). "Several cross-sectional studies indicated associations between serum 25(OH)D concentration and inflammatory markers: In Spanish school children, low serum 25(OH)D was associated with high IL-6 in children with overweight/obesity as well as with increased CRP in children with obesity." (PMID 39231874, 2024). "Obesity-associated inflammation is marked by increased serum CRP levels." (PMID 39372725, 2024). "In addition, close associations between obesity and CRP levels have been documented in several population-based studies." (PMID 39519093, 2024). "Additionally, a significant positive association was found for MMP-8 and smoking, CRP, and an inverse association with obesity and fasting time." (PMID 39917664, 2024). "However, studies have found that inflammatory cytokines such as CRP are associated with obesity and insulin resistance and are involved in modulating the effects of vitamin D on insulin resistance." (PMID 38160221, 2024). "Many ROS are associated with elevated inflammatory biomarkers, such as CRP and interleukins, which are crucial in the interplay between oxidative stress and the pro-inflammatory state linked to metabolic conditions like obesity, insulin resistance, and liver disease." (PMID 39201088, 2024).
Obesity (continued). "Prior research indicates that elevated CRP levels in children and adolescents are associated with an increased later-life risk of developing cardiovascular diseases, higher BMI and obesity, and depressive episodes." (PMID 38339813, 2024). "Elevated high-sensitivity CRP levels demonstrated a robust association with liver pathology, exhibiting commendable specificity in predicting fibrosis and steatosis in individuals with obesity." (PMID 39376593, 2024). "To further verify our conjecture, we used data from the National Health and Nutrition Examination Survey (NHANES) to evaluate the association of CRP with knee pain in the US adult population and explore whether this association is mediated by obesity." (PMID 39222043, 2024). "In addition, obesity is a major factor associated with C-reactive protein (CRP) concentration, a marker of systemic inflammation in rheumatoid arthritis." (PMID 38824226, 2024). "Therefore, although the exact association of nap duration with IL-6 as well as CRP is unclear, excessive napping probably leads to increased levels of IL-6 and CRP, increasing the risk of obesity and subsequent T2DM." (PMID 38590820, 2024). "Moreover, high serum levels exhibit a positive association with baseline glucose and triglycerides levels, obesity, insulin resistance, and C-reactive protein (CRP), a marker of inflammation." (PMID 39335666, 2024). "Additionally, an early study investigating the association between overweight/obesity and low-grade systemic inflammation, as measured by serum CRP levels, found a correlation between higher BMI and elevated CRP concentrations." (PMID 39201076, 2024). "Conversely, factors such as chronic inflammation (as indicated by insulin resistance), obesity, smoking, elevated levels of tumor necrosis factor and C-reactive protein, or lower serum albumin levels have been linked with higher serum cystatin C levels, leading to lower eGFRcys according to mGFR." (PMID 39125705, 2024). "Interestingly, we observed that CRP mediated the association of obesity (i.e., increased BMI and WC) with acute bronchitis and pneumonia, while IL-6 mediated the effects of BMI and WC on pneumonia." (PMID 39337223, 2024). "We hypothesized that higher circulating CRP levels were associated with poorer BC prognosis and that such an association was most pronounced in patients with obesity." (PMID 38914635, 2024). "The aims of this study were to examine the effect of obesity on the relationship between peripheral and gingival CRP levels and to examine the association of gingival CRP levels with clinical periodontal measures and gingival fluid inflammatory cytokines in periodontally healthy obese individuals." (PMID 38138192, 2023). "In line with this, obesity is often characterized by low-grade systemic inflammation, and the visceral fat area is independently associated with white blood cell count and high-sensitivity CRP (hs-CRP) levels." (PMID 37238973, 2023). "Since CRP is a proinflammatory protein, we hypothesized that increased levels of CRP in the gingival tissues of obese individuals would promote gingival inflammation and may explain the increased susceptibility to periodontitis in obesity." (PMID 38138192, 2023). "Elevated CRP serum levels are a risk factor for atherosclerosis, MetS, and obesity." (PMID 36839394, 2023). "Overweight/obesity was significantly associated with being male (P = 0.003), having a family history of heart attack (P = 0.038), and having high levels of lipid profile and hs-CRP." (PMID 38090421, 2023). "In the present study, due to the PA alleles in the CRP gene, heterozygous carriers could exhibit impaired ability to produce functional CRP in both liver and adipose tissue, therefore explaining a weaker effect of obesity on serum CRP for PA mutation carriers." (PMID 37493001, 2023).
Obesity (continued). "The primary strength of this study was that our study quantitatively shows for the first time the effects of overweight/obesity and high levels of HbA1c on inflammation, and provides scientific evidence for the prevention and treatment of related diseases caused by hs-CRP." (PMID 37215204, 2023). "Declines in PON1 activity were independently associated with elevated CRP in boys with obesity." (PMID 37372026, 2023). "In addition, IL-6, TNF-α, and CRP are repeatedly found to be elevated in a myriad of conditions linked to inflammation, such as obesity and smoking." (PMID 37213604, 2023). "Additionally, nocturia is also related to general obesity, increased serum CRP, and multiple cardiometabolic risk factors." (PMID 38186694, 2023). "Notably, IL-6 produced by visceral adipose depots is drained directly into the portal circulation and contributes to obesity-associated production of C reactive protein (CRP), a clinical index of cardiovascular risk." (PMID 37509065, 2023). "Obesity is associated with mild inflammation, and it is a state or condition that actively participates in regulating both physiological and pathological inflammatory processes by releasing pro-inflammatory cytokines, such as C-reactive protein (CRP)." (PMID 38162517, 2023). "Weight loss has been shown to lower hs-CRP and CRP concentrations in adults with obesity." (PMID 37139450, 2023). "Moreover, several studies have shown a positive association between obesity, type 1 diabetes, and increased serum CRP levels." (PMID 36837520, 2023). "Furthermore, we aimed to elucidate the clinical relevance of the identified genetic factors by estimating the gene–obesity interaction as well as the relative risk for a set of CRP‐associated diseases." (PMID 37493001, 2023). "In an in vitro study, PC12 cells treated with H2O2 reduce pro-inflammatory markers associated with obesity, such as C-reactive protein (CRP), interleukin (IL)-6, and tumor necrosis factor (TNF)-α, leading to reduced oxidativestress-induced neurotoxicity in PC12 cells treated with H2O2." (PMID 37835263, 2023). "In the general population, obesity has also been associated with higher CRP levels." (PMID 38003780, 2023). "However, enterolactone urinary levels were associated with reduced obesity, reduced C-reactive protein, reduced blood pressure, reduced triglycerides, higher serum–HDL-cholesterol, and a lower occurrence of metabolic syndrome." (PMID 36678189, 2023). "However, the high urine–enterolactone concentrations were inversely associated with obesity, abdominal obesity, high serum C-reactive protein, high serum triglycerides, low serum HDL cholesterol, and a reduced risk of metabolic syndrome." (PMID 36678189, 2023). "Prominent among the elevated obesity-associated circulating adipokines and cytokines are the C-reactive protein (CRP), Semaphorin-3C (Sema3C), Tumor Necrosis Factor-alpha (TNF alpha), Interleukin-6 (IL-6), Monocyte Chemoattractant Protein-1 (MCP1), and Interleukin-8 (IL-8)." (PMID 38068748, 2023). "However, as far as we know, little is known about their combined effects of HbA1c level and overweight/obesity on increased risk of hs-CRP, especially in Chinese adults." (PMID 37215204, 2023). "Both serum CRP level and obesity play an important role in the risk assessment of cardiovascular diseases, therefore exploring the effect modification due to genetic factors and obesity could guide a personalized risk prediction." (PMID 37493001, 2023). "There was a significant association between overweight/obesity and male gender (p=0.003), as well as having a family history of heart attack (p=0.038), high lipid profile, and high-sensitivity C-reactive protein (hs-CRP)." (PMID 38090421, 2023). "Interestingly, the CRP levels at which obesity and HTG influenced the association of depression with RA were found to be distinct." (PMID 38455932, 2023).